CYP2S1 (cytochrome P450 family 2 subfamily S member 1)
Diseases named in the same sentence as CYP2S1 in open-access papers (continued):
Sharing a sentence is not in itself a finding about the gene and the disease.
thyroid cancer (2 papers, 2020 to 2021). "In this study, we identify CYP2S1 as a synthetic lethal partner of BRAFV600E in thyroid cancer, and preliminarily reveal the mechanism underlying a synthetic lethal interaction between CYP2S1 and BRAFV600E." (PMID 32913191, 2020). "This AHR/CYP2S1 feedback loop strongly amplified oncogenic role of BRAFV600E in thyroid cancer cells, thereby causing synthetic lethal interaction between CYP2S1 and BRAFV600E." (PMID 32913191, 2020). "This AHR/CYP2S1 feedback loop strongly amplifies oncogenic role of BRAFV600E in thyroid cancer cells, thereby causing synthetic lethal interaction between CYP2S1 and BRAFV600E." (PMID 32913191, 2020). "This raised the possibility that targeting CYP2S1 may be an effective strategy for BRAFV600E-mutated thyroid cancers." (PMID 32913191, 2020). "Thus, we suppose that increased expression of CYP2S1 in BRAFV600E-mutated thyroid cancer cells lead to the concentration of certain metabolic products such as 12-HHT and 5-oxoETE, thereby promoting malignant phenotypes of cancer cells." (PMID 32913191, 2020). "In addition, its expression was strongly associated with BRAFV600E mutation, suggesting that CYP2S1 may be selectively essential in BRAFV600E mutated thyroid cancers." (PMID 32913191, 2020). "This AhR/CYP2S1 feedback loop strongly amplifies oncogenic role of BRAFV600E in thyroid cancer cells." (PMID 35002727, 2021). "Next, to further validate therapeutic potential of Au-si-CYP2S1 in vivo, we established xenograft and transgenic mouse models of thyroid cancer." (PMID 32913191, 2020). "Taken together, our data indicate that CYP2S1 is an effective therapeutic target in BRAFV600E-driven thyroid cancers." (PMID 32913191, 2020). "Altogether, our data demonstrate CYP2S1 as a synthetic lethal partner of BRAFV600E in thyroid cancers, and indicate that targeting CYP2S1 will provide a new therapeutic strategy for BRAFV600E mutated thyroid cancers." (PMID 32913191, 2020). "Collectively, our data indicate the existence of the CYP2S1-AHR feedback loop, contributing to malignant phenotypes of BRAFV600E-driven thyroid cancers, and also make rationalization of the synthetic lethal interaction between CYP2S1 and BRAFV600E." (PMID 32913191, 2020). "Taken together, we speculate that CYP2S1 may be a potential synthetic lethal partner of BRAFV600E in thyroid cancers." (PMID 32913191, 2020). "In addition, Au-si-Cyp2s1 obviously inhibited tumor growth and weight in transgenic model of thyroid cancer, also supported by Ki-67 and CYP2S1 staining." (PMID 32913191, 2020). "Thus, our data demonstrate that CYP2S1 is a potential synthetic lethal partner of BRAFV600E, and also provide an alternative therapeutic strategy for BRAFV600E-mutated thyroid cancers by targeting CYP2S1." (PMID 32913191, 2020). "Here, we identified CYP2S1 as a synthetic lethal partner of BRAFV600E in thyroid cancers." (PMID 32913191, 2020). "As expected, our data demonstrated that Au-si-CYP2S1 selectively inhibited BRAFV600E-mutated thyroid cancer cells, while almost did not affect the growth of BRAFV600E wild-type ones." (PMID 32913191, 2020). "As expected, CYP2S1 knockdown strongly induced cell apoptosis in BRAFV600E-mutated thyroid cancer cell lines, but not in BRAF wild-type ones." (PMID 32913191, 2020). "The results showed that CYP2S1 knockdown significantly inhibited cell proliferation in BRAFV600E-mutated thyroid cancer cell lines, but not in BRAF wild-type ones, also supported by colony formation assays." (PMID 32913191, 2020). "Besides, our data also showed that CYP2S1 knockdown selectively decreased migration and invasion ability of BRAFV600E-mutated thyroid cancer cells compared to the control." (PMID 32913191, 2020). "Moreover, unlike thyroid cancer, CYP2S1 expression was downregulated in BRAF-mutated colon adenocarcinomas compared to BRAF wild-type ones." (PMID 32913191, 2020).
thyroid cancer (continued). "Similarly, Au-si-CYP2S1 selectively inhibited cell proliferation in BRAFV600E-mutated thyroid cancer cells, but not in BRAF wild-type ones." (PMID 32913191, 2020). "We also designed Au-si-Cyp2s1 to target Cyp2s1 in NIH3T3 cells and transgenic model of thyroid cancer." (PMID 32913191, 2020). "CYP2S1 knockdown selectively inhibited cell proliferation, migration, invasion and tumorigenic potential in nude mice, and promoted cell apoptosis in BRAFV600E mutated thyroid cancer cells, but not in BRAF wild-type ones." (PMID 32913191, 2020).
adenoma (1 paper, 2025). A neoplasm arising from the epithelium. "The results revealed that the number of adenomas in the APCMin/+;CYP2S1-/- mice increased significantly compared to APCMin/+ mice." (PMID 40740230, 2025). "A significant increase in the number of adenomas and an increase in cell proliferation and angiogenesis suggested that CYP2S1 knockout promoted the development of intestinal adenomas in mice." (PMID 40740230, 2025). "Compared with those of APCMin/+mice, the intestinal tracts of APCMin/+;CYP2S1-/- mice presented obvious hyperplasia and more adenomas." (PMID 40740230, 2025). "We found that CYP2S1 knockout in APCMin/+ mice led to an increased number of adenomas, accelerated tumor progression and enhanced proliferation and angiogenesis of adenomas." (PMID 40740230, 2025).
ductal carcinomas (1 paper, 2022). "Low nuclear CYP2S1 was associated with HER2‐negative disease (χ2 = 6.396, df = 1, p = 0.011), grade 3 tumours (χ2 = 9.422, df = 2, p = 0.009), intermediate NPI (χ2 = 7.415, df = 2, p = 0.025), mitosis (χ2 = 12.492, df = 2, p = 0.002), and ductal carcinomas (χ2 = 17.161, df = 6, p = 0.007)." (PMID 35902379, 2022).
glaucoma (1 paper, 2021). Increased pressure in the eyeball due to obstruction of the outflow of aqueous humor. "Consistently, another relative enzyme, CYP2S1, increased in rat retina in the glaucoma model based on optic nerve transaction." (PMID 34356513, 2021).
hepatic disease (1 paper, 2011). "To further elucidate the expression of CYP2S1 in the mouse liver, we isolated both hepatocytes and HSCs and measured mRNA levels of 6 CYPs, which were chosen based on their known liver expression, roles in retinoid metabolism and/or proposed roles in hepatic disease." (PMID 21949825, 2011).
Hepatic fibrosis (1 paper, 2011). The presence of excessive fibrous connective tissue in the liver. "Thus, we propose that CYP2S1-mediated retinoid catabolism may play a role in the loss of lipid droplets and retinyl ester content in HSCs undergoing activation in the early stages of hepatic fibrosis." (PMID 21949825, 2011). "Furthermore, we show that Cyp2s1 expression is elevated in vivo by carbon tetrachloride-mediated induction of hepatic fibrosis." (PMID 21949825, 2011).
intestinal tumors (1 paper, 2025). "In this study, APCMin/+;CYP2S1-/- mice were bred to investigate the number of intestinal tumors incidence and morphology in CYP2S1-deficient APCMin/+ mice." (PMID 40740230, 2025).
invasive breast carcinoma (1 paper, 2022). A carcinoma that infiltrates the breast parenchyma. "This study assessed CYP2S1 and CYP2W1 protein expression in a large independent cohort of early‐stage invasive breast cancer patients (Nottingham cohort) to evaluate associations with various clinicopathological and survival parameters." (PMID 35902379, 2022). "Protein expression of CYP2S1 and CYP2W1 was assessed in early‐stage invasive breast cancers (n = 1,426) using immunohistochemistry and correlated with various clinicopathological parameters and survival." (PMID 35902379, 2022).
ovarian carcinoma (1 paper, 2023). A malignant neoplasm originating from the surface ovarian epithelium. "Moreover, CYP2S1 was found to be more highly expressed in ovarian cancers than in healthy normal ovaries, and significant CYP2S1 expression was identified in metastatic ovarian tumors compared to primary ovarian cancers and healthy normal ovaries." (PMID 38001897, 2023).
papillary thyroid cancers (1 paper, 2020). "First, we found that CYP2S1 was highly expressed in papillary thyroid cancers (PTCs) compared to normal thyroid tissues, particularly in conventional PTCs (CPTCs) and tall-cell PTCs (TCPTCs), and its expression was positively associated with BRAFV600E mutation." (PMID 32913191, 2020).
stomach adenocarcinoma (1 paper, 2023). "Furthermore, the super-enhancers of CYP2S1 were also stomach adenocarcinoma (STAD)–specific." (PMID 37207350, 2023).
tuberculosis (1 paper, 2022). A chronic, recurrent infection caused by the bacterium Mycobacterium tuberculosis. "In the present study, we would like to explore whether Cytochrome P450 2S1 (CYP2S1) rs338599 polymorphism confers risk to anti‐tuberculosis drug‐induced liver injury (ADLI) and provide evidence of being used as novel marker for ADLI risk prediction." (PMID 35535391, 2022). "Cytochrome P450 2S1 (CYP2S1) is a family monooxygenase, which plays an important role in the metabolism of various substances including Anti‐tuberculosis drugs." (PMID 35535391, 2022).
tumor (13 papers, 2014 to 2025). "Cytoplasmic CYP2S1 was additionally associated with patients ≥50 years (p < 0.001), estrogen receptor (ER)‐positive tumours (p = 0.011), and high nuclear pleomorphism (p = 0.003)." (PMID 35902379, 2022). "In addition, some genes (glutathione S-transferase mu 1, cyclin D1and cytochrome P450 family 2 subfamily S member 1) in risk model was show significant difference between normal and tumor tissues." (PMID 36203457, 2022). "CYP2S1 was significantly detected in T3 and T4 tumours, with a sequence coverage of 7% and a Mascot score of 88, while CYP20A1 was detected across pT2 and T4 tumours." (PMID 41174467, 2025). "Among them, CCND1, GSTM1 and CYP2S1 were differentially expressed in normal tissues and tumor tissues, while the other two genes had the same expression trend as the database analysis." (PMID 36203457, 2022). "The thromboxane (TxA2, TxB2) and 12-HHTre synthase Tbxas1 is detected in macrophages, while 12-HHTre synthase Cyp2s1 is expressed in PanIN and tumor cells." (PMID 36277993, 2022). "The association of low CYP2S1 mRNA with HER2‐negative status, and low CYP2S1/CYP2W1 with luminal A tumours agrees with results obtained in the Nottingham cohort protein assessments." (PMID 35902379, 2022). "More importantly, we established a collaurum-based siRNA delivery system, and successfully delivered CYP2S1-specific siRNA to tumor site in both xenograft and transgenic mouse models using this system." (PMID 32913191, 2020). "Because CYP2S1 can be expressed in several tumor cells sensitive to ellipticine, the data found in this work suggest that this CYP can contribute to the ellipticine antitumor activity in these cells." (PMID 27110039, 2016). "No protein of the anticipated size corresponding to CYP2B6 or CYP2S1 was detected in the tumor tissues by the commercially available (CYP2B6) or homemade (CYP2S1) antibodies." (PMID 25526449, 2014). "Consequently, tumour-associated CYP450 isoforms, such as CYP1A1, CYP1B1, CYP2S1, and CYP2W1—have become a focus for the development of novel anticancer therapies." (PMID 41174467, 2025). "The presence of CYP2W1 in HNSCC further reinforces its potential functional role in cancerous cells, expanding its relevance beyond CRC, while CYP2S1 has been implicated in inflammatory responses, potentially contributing to the aggressive nature of HNSCC tumours." (PMID 41174467, 2025). "Utilization of the tumor cells highly expressing CYP2S1 is planned to be utilized for such studies." (PMID 27110039, 2016). "PARPα induces the downregulation of CYP2S1 and CYP1B1 expression, which leads to tumor cycle arrest, the induction of apoptosis, and the reduction of tumor cell migration, inhibiting metastatic development." (PMID 40005270, 2025). "In CRC models, the predominant expression of CYP2W1, CYP2S1, CYP1B1, and CYP2J2 suggests their potential functional involvement in tumour metabolism, xenobiotic processing and disease progression." (PMID 41174467, 2025). "Promoting the expression of CYP2S1 can enhance the effect of oxaliplatin on COAD cells, while knocking down CYP2S1 can promote the expression of prostaglandin E2, thus promoting tumor proliferation." (PMID 36203457, 2022). "Tumor cells express synthases TBXAS1 (TXA2, TXB2, 12-HHTre) and CYP2S1 (12-HHTre), and some subclusters are enriched for PGE2 synthase PTGES or prostacyclin synthase PTGIS." (PMID 36277993, 2022). "Purified protein standards (CYP2B6, CYP2S1, and CYP3A4), MT-3 cells lysate (AKR1C2), human liver lysate (AKR1C1 and CBR1), and a pool of tumor samples (AKR7A3) were used as a calibrator for comparison of variability among membranes." (PMID 25526449, 2014). "Tumor cells express genes required to produce PGE2 (Ptges) and 12-HHTre (Cyp2s1)." (PMID 36277993, 2022).
tumor (continued). "CYP2S1 and CYP2W1 expression was observed across all cores with staining intensity varying from weak to strong in both the cytoplasm and nucleus, and with heterogeneous expression observed between adjacent tumour cells." (PMID 35902379, 2022). "The mRNA expression of CCND1 and CYP2S1 genes was high in COAD tumor tissues, while the mRNA expression of GSTM1 gene was low in COAD tumor tissues, and the difference was statistically significant, which was consistent with the previous results of TCGA database and GEPIA2 data analysis." (PMID 36203457, 2022). "Therefore, identifying CYP2S1 and CYP2W1 expression in patient tumours may help in the selection of individuals that could potentially benefit from treatment with chemotherapeutic agents that require these enzymes for metabolism." (PMID 35902379, 2022). "In addition, mRNA isolated from tissues contains a mixture of tumour, stromal, and immune cells, which may result in dilution effects as opposed to IHC, wherein CYP2S1 and CYP2W1 protein expression was assessed only in tumour cells." (PMID 35902379, 2022). "CYP2S1, CYP2U1 and CYP4X1 exhibited the highest percentage of strong immunoreactivity in contrast to other isoforms such as CYP2J and CYP3A4, which displayed no reactivity in majority of the tumours." (PMID 33809117, 2021).
cancer (5 papers, 2020 to 2025). A tumor composed of atypical neoplastic, often pleomorphic cells that invade other tissues. "To clarify the clinical significance of CYP2S1, we evaluated its association with prognosis in cancer patients." (PMID 40740230, 2025). "Multivariate Cox proportional hazards analysis for predictors of overall survival for cytoplasmic CYP2S1 expression in ER‐positive cancers." (PMID 35902379, 2022). "CYP2S1 and CYP2W1 mRNAs were also associated with luminal A cancers in the METABRIC cohort, all of which are consistent with the reported role of CYP enzymes in the metabolism and oxidation of estrogens." (PMID 35902379, 2022). "Previous studies have suggested that genes located in this region, such as ZNF217, GPC3, and CYP2S1, could contribute to the development and progression of cancer." (PMID 40354349, 2025). "As expected, the CYP2S1 exhibited a higher gene expression in STAD than in other cancers." (PMID 37207350, 2023). "The involvement of CYP2W1 in the metabolism and oxidation of estrogen, along with the strong association of cytoplasmic CYP2S1 and nuclear CYP2W1 protein with ER‐positive cancers, suggests that these enzymes may be important as prognostic markers in ER‐positive disease." (PMID 35902379, 2022). "From the METABRIC cohort, low CYP2S1 mRNA expression was significantly associated with positive progesterone receptor (PgR) (χ2 = 10.400, df = 1, p = 0.001), HER2‐negative status (χ2 = 11.652, df = 1, p = 0.001), and luminal A cancers (χ2 = 15.377, df = 5, p = 0.009)." (PMID 35902379, 2022). "Interestingly, COAD was the cancer type where RNF43, CYP2S1 and LIF showed the highest expression, suggesting that these three genes’ cancer-specific functions might be attributed to their adjacent super-enhancers." (PMID 37207350, 2023).
CYP2S1 also shares sentences with these, for which no sentence is quoted: Obesity (2 papers); colon adenocarcinoma (1); colorectal tumor (1); head and neck cancer (1); lung adenocarcinoma (1); renal carcinoma (1); tall (1).